IL10 (interleukin 10)
Diseases named in the same sentence as IL10 in open-access papers (continued):
Sharing a sentence is not in itself a finding about the gene and the disease.
atherosclerosis (continued). "In aged apolipoprotein E-deficient mice, a model for atherosclerosis, IL-10+ B lineage cells, many of them exhibiting an CD138+ plasma cell phenotype, have been also found within artery tertiary lymphoid organs, i.e., atherosclerosis-associated lymphoid aggregates surrounding the affected arteries." (PMID 31214168, 2019). "This may be the result of the effort with the increased synthesis (levels) of IL-10 to protect/prevent atherosclerosis in the whole study group in this study, which had patients with coronary artery symptoms and a potential diagnosis of CAD." (PMID 29742255, 2018). "Increased IL-10 levels may create an anti-inflammatory environment and lead to protection against atherosclerosis development." (PMID 29593532, 2018). "Overexpression of IL-10 in macrophages suppresses atherosclerosis in hyperlipidemic mice." (PMID 29545532, 2018). "Overall, it is intriguing that IL-1α may exert effect on progression of atherosclerosis in Rgp44-immunized mice whereas the anti-inflammatory cytokines IL-5 and IL-10 are crucial for possible atheroprotection in Pg-immunized mice." (PMID 29329335, 2018). "In a murine model of atherosclerosis, IDO deficiency was associated with a significant increase in atherosclerotic lesion size and surrogate markers of plaque vulnerability, through downregulation of IL-10 production." (PMID 29278387, 2017). "We hypothesized that AngII-induced regulatory B cells prevented the progression of atherosclerosis through their IL-10 production." (PMID 28646220, 2017). "Absence of DNGR1 was shown to reduce atherosclerosis development in a context of moderate hypercholesterolemia, associated with an increase in the expression of interleukin-10 (IL-10)." (PMID 28771609, 2017). "If IL-10 is truly related to new major cardiovascular events, then periodontal disease might have a detrimental effect on atherosclerosis by increasing the levels of IL-10, as demonstrated in this study." (PMID 27556206, 2016). "Furthermore, the role of TNF-α, IFN-γ, IL-1β, IL-6, IL-8, IL-4 and IL-10 in the pathogenesis of atherosclerosis in carotid artery post-carotid endarterectomy has been documented." (PMID 27271180, 2016). "IL-10 global knock out mice exhibit unregulated inflammatory activity, which is exemplified by enhanced TNF accumulation and thus is associated with a variety of pathogenic outcomes including atherosclerosis." (PMID 26808574, 2016). "Interleukin (IL)-10 is another important immune regulator that may be important in the pathogenesis of atherosclerosis." (PMID 25948070, 2015). "Furthermore, another important role of IL-10 in atherosclerosis is its ability to alter lipid metabolism in macrophages." (PMID 25948070, 2015). "Upregulation of IL-10 locally or systemically reduces atherosclerosis development in mouse models." (PMID 24741576, 2014). "Impaired anti-inflammatory macrophage signaling through a CD163/pAkt/IL-10 axis may thus represent a possible Hp2-2 disease mechanism in atherosclerosis." (PMID 23710416, 2013). "Animal experiments have shown that the absence of IL-10 leads to an increased susceptibility to atherosclerosis in IL-10 knockout mice." (PMID 24040186, 2013). "IL-10 may have therapeutic potential in various inflammatory diseases, including atherosclerosis, as it can inhibit oxLDL-induced foam cell formation and apoptosis in macrophages and endothelial cells." (PMID 23718574, 2013). "Thus, as an important anti-inflammatory cytokine, interleukin-10 (IL-10) has been proposed to protect against atherosclerosis progression." (PMID 24040186, 2013). "Mice null for IL-10 develop significantly more atherosclerosis than controls." (PMID 23248624, 2012). "The role of IL-10 has been clearly established in mouse model of atherosclerosis." (PMID 22556042, 2012). "Moreover, oral or nasal mucosal immunization with Mycobacterium Hsp65 that resulted in protection against atherosclerosis was also related to IL-10 production." (PMID 19754943, 2009).
atherosclerosis (continued). "Although SWCNT exposure was associated with atherosclerosis acceleration, we did not observe significant differences in the plasma levels of IL-6, IL-10, MCP-1, TNF-α, or IFN-γ." (PMID 17431486, 2007). "FLI1 regulates the expression of metalloproteases (MMP-1, MMP-3, and MMP-10) and the pro-inflammatory cytokine IL-10; therefore, during chronic inflammatory conditions, such as AR and atherosclerosis, FLI1 down-regulation could attenuate tissue damage associated with inflammatory responses." (PMID 39767648, 2024). "However, the role of Breg IL-10 in atherosclerosis is debated within the literature." (PMID 38813699, 2024). "Similarly, IL-10 also offers protection against atherosclerosis development." (PMID 38558816, 2024). "In addition, IL-10 was a poor biomarker regarding subclinical atherosclerosis." (PMID 37629526, 2023). "Furthermore, SARS-CoV-2 leads to cytokine outburst, including IL-6, IL-1b, IL-2, IL-10, and monocyte chemoattractant protein-1 (MCP-1), which are also associated with vascular dysfunction and vascular disease such as atherosclerosis, abdominal aortic aneurysm, varicose veins and hypertension." (PMID 36211676, 2022). "Of note, in hypercholesterolemic mice, atherosclerosis was accelerated by administration of LDL-induced DCs and attenuated by immunotherapy with DCs treated with ApoB100 and IL-10, indicating that atherosclerosis could be modulated by modifying the maturation of DCs." (PMID 36405994, 2022). "Notwithstanding the fact that IL-10 induction has been proposed as a pillar of curcumin immunomodulatory actions, surprisingly IL-10 induction has not been consistently addressed in preclinical studies exploring the potential of curcumin for atherosclerosis or MS/EAE treatment." (PMID 34305950, 2021). "Moreover, PD-1 expressing CD8+ T cells from patients with atherosclerosis produced more anti-atherogenic IL-10 and less pro-atherogenic cytokines (IFNγ, TNFα) compared to PD-1−CD8+ T cells, further supporting a protective role for PD-1 in T cell-mediated immunity." (PMID 34790707, 2021). "Therefore, IL-10 plays a role in the reduction of inflammation in atherosclerosis." (PMID 32346605, 2020). "In addition, the HA-mac phenotype could produce anti-inflammatory IL-10 and possesses atherosclerosis protective effect." (PMID 30923552, 2019). "Indeed, previous studies clarified that TGF-β is a stabilizing factor in human atherosclerotic plaques and IL-10 knockout or IL-10 transgene could significantly exacerbate or ameliorate the development of atherosclerosis." (PMID 31686988, 2019). "Work from mouse models suggests a potential pro-atherogenic function of iNKT cells; however, human studies have suggested that iNKT cells may have a protective role in the early stages of atherosclerosis by promoting atherosclerosis resolution via increased IL-10 production." (PMID 28853005, 2018). "Furthermore, IL-10 cytokine alleviates inflammation in atherosclerosis model." (PMID 27070323, 2016). "Evidence regarding the anti-inflammatory effects of IL-10 to the neo-intimal thickening and restenosis following arterial injury is limited with some studies showing that IL-10 plays an important role in the suppression of intimal hyperplasia and restenosis and atherosclerosis." (PMID 26808574, 2016). "Although we could not find any genetic risk factor with IL-10 and cIMT, this does not exclude the importance of this anti-inflammatory cytokine in the pathogenesis of atherosclerosis." (PMID 25948070, 2015).
atherosclerosis (continued). "This is the first report to our knowledge to assess the relationship of 25(OH)D concentration with MMP-9 and IL-10 in an ESRD population, and may help to shed light on mechanisms by which vitamin D deficiency is associated with an increased risk of atherosclerosis and cardiovascular disease." (PMID 21600051, 2011). "Similar findings in the atherosclerosis model support our data, which showed that HSP65‐induced oral tolerance led to decreased disease severity through increased IL‐10 and reduced IFN‐γ production." (PMID 40745935, 2026). "In atherosclerosis, THSD1 expression is downregulated by pro-atherogenic factors such as TNFα and upregulated by the anti-atherogenic cytokine IL-10, suggesting a dynamic regulatory role in atherosclerosis prevention." (PMID 40564011, 2025). "Treg protects against atherosclerosis by secreting IL-10 and TGF-β, among which IL-10 is an anti-inflammatory factor and TGF-β can stabilize plaque formation." (PMID 41268556, 2025). "Treg cells are known to release IL-10 and TGF-β, both of which have exhibited a protective effect on the progression of atherosclerosis, as demonstrated in both animal and clinical studies." (PMID 38774876, 2024). "Conversely, during the stages of atherosclerosis regression, innate immune cells can express ACE (angiotensin-converting enzyme), IL-4, and IL-10 and TGF-β to attract reparative lymphocytes like Th2 cells." (PMID 38774876, 2024). "Similarly, IL-10 has a crucial role in Treg-mediated immune modulation, especially in response to pathogens or external stimuli-induced inflammatory reactions.IL-10 produced by Tregs plays a key role in resisting atherosclerosis and modulating the formation of atherosclerotic plaques." (PMID 38558816, 2024). "In contrast, anti-inflammatory cytokines such as IL-5, IL-10, IL-19, IL-35, and transforming growth factor (TGF)-β inhibit vascular inflammation and atherosclerosis." (PMID 39273602, 2024). "Conversely, B2 cells participate in adaptive immune responses and secrete cytokines IL-10 and TNF-α, which influence Treg development and potentially promote the formation of atherosclerosis." (PMID 38143759, 2023). "CD14++CD16− produces low levels of tumor necrosis factor alpha (TNF-α) and high amount of IL-10, whereas CD14+CD16++ secretes high levels of pro-inflammatory cytokines promoting atherosclerosis." (PMID 37600028, 2023). "Chronic low-grade inflammation also contributes significantly to the pathogenesis of atherosclerosis, due to the effects of tumor necrosis factor-alpha (TNF-α) and interleukin-10 (IL-10)." (PMID 37628963, 2023). "TLR7 can inhibit inflammation in atherosclerosis by secreting TNF-α and IL-10, so it is regarded as a prognosis marker in severe atherosclerosis patients." (PMID 38524701, 2023). "The level of the pro-inflammatory factor IL-1β was significantly decreased and the levels of anti-inflammatory factors eNOS, TGFβ, Arg1, and IL-10 were significantly increased after GLSP treatment in early and advanced atherosclerosis." (PMID 36923537, 2023). "Correspondingly, studies in animal models have also demonstrated that Tregs can secrete anti-inflammatory cytokine IL-10 and TGF in stable plaque- β and inhibit pro-inflammatory T cell proliferation, delaying atherosclerosis occurrence and development." (PMID 35509837, 2022). "The converse is also true; stimulation of PD-1 signalling in mice inhibits atherosclerosis by modulating T-cell activity – reducing interferon-gamma producing CD4 + T cells and increasing atheroprotective IL-10 secreting CD4 + T-cells." (PMID 36461057, 2022). "Thus it has been difficult to define a protective effect of IL-10 on atherosclerosis and this has limited the potential application of IL-10 as a therapeutic approach for the treatment of ASCVD in clinical trials." (PMID 36110841, 2022). "The evidence that IL-10 and NOS3 play a positive role in inhibiting the development of atherosclerosis has been discussed elsewhere." (PMID 35059464, 2022).
atherosclerosis (continued). "TH1CD4+ lymphocytes accelerate the formation of atherosclerosis, whereas regulatory T-cells can inhibit atherosclerosis by secreting cytokines, such as transforming growth factor (TGF)-α and IL-10." (PMID 35211020, 2022). "The importance of IL-10 and TGF-β for attenuating atherosclerosis was subsequently confirmed by additional studies." (PMID 35936011, 2022). "Interesting results on the location of atherosclerosis and genetic variation in 9 SNP of such genes as TNF-alfa, IL-1b, IL-10, and TGF-b1 were obtained by pathomorphologists studying this phenomenon among Japanese patients." (PMID 33801199, 2021). "Regulatory T cells secrete atheroprotective IL-10 and TGF-β to attenuate atherosclerosis, while Th1 cells promote atherosclerosis." (PMID 33613306, 2021). "Additionally, it could be shown that PCSK9 aggravates atherosclerosis in apolipoprotein-E deficient mice, which was associated with an increased expression of inflammatory cytokines such as TNF-α, IL-1β, IL-10, MCP-1, and IL-8 to directly facilitate the process of inflammation." (PMID 34884827, 2021). "For examples, cDC1s can drive the recruitment of IL-10-expressing CD25+Foxp3+ Tregs in nephrotoxic AKD, liver IRI, crescent glomerulonephritis, as well as atherosclerosis." (PMID 34234783, 2021). "Gene deletion, or inhibition of IL-10 or TGF-β with neutralizing antibodies, aggravates atherosclerosis in mice and exacerbates effector Th1 and Th2 responses." (PMID 33805071, 2021). "On the other hand, anti-inflammatory factors, including interleukin-10 (IL-10) and transforming growth factor b (TGF-β), act as protective factors in atherosclerosis." (PMID 34447794, 2021). "This study identified that rSj-Cys stimulated Treg and M2 macrophages to secrete regulatory cytokines IL-10 and TGF-β that inhibit oxidized lipid-induced inflammation and atherosclerosis through inhibiting the TLR2/Myd88 pathway." (PMID 34901005, 2021). "CD4+CD25+Foxp3+ Treg exerts immunomodulatory effects by releasing anti-inflammatory cytokines IL-10 and TGF-β to inhibit the development of atherosclerosis possibly through promoting the conversion of M1 to M2 macrophages." (PMID 34901005, 2021). "However, given that both TGF-β and IL-10 are not exclusively produced by Tregs, but can also be released by macrophages, these studies did not provide evidence of causality between Tregs and protection against atherosclerosis." (PMID 33805071, 2021). "This is in line with the use of APN treatment in atherosclerosis; pretreatment with APN reduces LPS-stimulated TNF-α production and stimulates production of IL-10 in human and pig macrophages." (PMID 33616153, 2021). "The prominent passage regulation occurred in LPS/IL-1-mediated inhibition of RXR function, IL-10 signaling, NRF2-mediated oxidative stress response, and atherosclerosis signaling." (PMID 32855961, 2020). "In studies, M2 macrophages are found to secrete IL-10 and TGF-β to enhance atherosclerosis regression." (PMID 32346605, 2020). "Cytokine IL-6, TNF-α, and MCP-1 promote atherosclerosis and are classified as pro- cytokines, while cytokine IL-10 and TGF-β suppress the formation and progression of atherosclerosis and are categorized as anti-atherogenic cytokines." (PMID 32611832, 2020). "Here, we found that compared with the Control group mice, serum levels of TNF-α, IL-1β, IL-6 were significantly increased, and IL-10 and ADPN levels were significantly decreased in HFD-induced atherosclerosis mice (Model group; all p < 0.001)." (PMID 32231564, 2020). "Treg cells have been shown to produce IL-10 and TGF-β, and their protective roles against atherosclerosis have been suggested in in vitro and in vivo studies." (PMID 31307370, 2019). "In fact, potential therapies for the treatment of atherosclerosis such as mucosal administration of athero-antigens (HSP 65, oxLDL, apoB-100 peptides) have shown increments in production of IL-10, IL-4 and TGF-β." (PMID 29163168, 2017).
atherosclerosis (continued). "While IL-10 is known as antiinflammatory, the role of Lp-PLA2 in the process of atherosclerosis is poorly understood and controversely discussed in the literature." (PMID 28085888, 2017). "The laboratory indices of microinflammation include elevated blood levels of CRP and some cytokines, mainly IL-6, IL-18, IL-10, and TNF-alpha, which correlated with acceleration of atherosclerosis." (PMID 26236736, 2015). "Previously, we have shown that, analogous to this study, AAV/STAT3 gene delivery, with STAT3 being down-stream of interleukin 10 (IL10), is similarly able to substitute for IL10, again, for inhibiting atherosclerosis." (PMID 25236373, 2014). "Both IL-10 and STAT3 have been shown to inhibit atherosclerosis in an animal model, and both are in the same anti-inflammatory signal transduction pathway, with IL-10 acting through STAT3." (PMID 21915378, 2012). "The aim of this study was to confirm the possibility of using in vivo MRI to monitor IL-10 gene-transduced, MR contrast agent-labeled bone marrow cells (BMC) that were recruited to atherosclerosis for preventing the progression of atherosclerotic disease." (PMID 21915349, 2011). "Atherosclerosis may also be a confounding factor with IL-10 analysis, since patient plasma IL-10 concentrations were similar to those of controls and reduced concentrations of plasma IL-10 have been noted in studies where plasma of patients with stroke has been compared to that of healthy controls." (PMID 17328808, 2007). "IL-10 was undetectable in all patients, regardless of the presence of atherosclerosis, and IL-18 was positive in only one patient (1.8%) who presented with MASLD, no atherosclerosis, and normal bilateral CIMT." (PMID 40299570, 2025). "Inflammatory modulators/biomarkers, such as IL-1α, IL-1β, IL-6, IL-12, IL-15, IL-18, and tumor necrosis factor α, or alternative anti-inflammatory cytokine IL-10, and adhesion molecules (ICAM-1, VCAM-1), involved in atherosclerosis progression have been shown to predict cardiovascular diseases." (PMID 37374202, 2023). "More recent studies revealed the specificity of the IL-10 cellular source, demonstrating the importance of T-cell-derived but not B-cell-derived IL-10 in taming the severity of atherosclerosis." (PMID 33562334, 2021). "Zhu and his colleagues found that the serum level of IL-10 in SLE patients with atherosclerosis was less than in that of the SLE patients without atherosclerosis." (PMID 34640445, 2021). "Therefore, in our opinion, high-concentration homocysteine affects the progression of atherosclerosis by increasing the secretion of proinflammatory cytokines secreted by PBMNCs, such as Il-1β, Il-6, RANTES, and by attenuating the secretion of Il-10." (PMID 34771080, 2021). "Cytokines involved in human atherosclerosis can be broadly classified as pro-inflammatory and pro-atherogenic (such as IL-1, IL-6, and TNF) or as anti-inflammatory and anti-atherogenic (such as IL-10 and IL-1rA)." (PMID 34076144, 2021). "In atherosclerosis, even though curcumin-induced IL-10 has not been explored previously, atheroprotective effects of high dose oral curcumin were related to Th2/Treg balance modulation in asthmatic ApoE-/- mice." (PMID 34305950, 2021). "In this regard, promising studies show the beneficial role of anti-inflammatory molecules, such as IL-10 or colchicine, in atherosclerosis, but they need to be further studied and they are still not used in the treatment of patients." (PMID 33153204, 2020).